HEY2 (hes related family bHLH transcription factor with YRPW motif 2)
Description:
Downstream effector of Notch signaling which may be required for cardiovascular development. Transcriptional repressor which binds preferentially to the canonical E box sequence 5'-CACGTG-3'. Represses transcription by the cardiac transcriptional activators GATA4 and GATA6.
Synonyms: bHLHb32; CHF1; GRL; HERP1; HRT2; HESR2; GRIDLOCK
Tractability: No criterion of Open Targets' tractability assessment is met for any kind of drug.
Gene: Protein-coding gene on chromosome 6 (125,747,664 to 125,761,269, forward strand). Ensembl gene ENSG00000135547.
Subcellular location: Nucleus
Subcellular location (Human Protein Atlas): Nuclear bodies; Aggresome
Pathways (Reactome):
Signal Transduction: NOTCH1 Intracellular Domain Regulates Transcription; NOTCH3 Intracellular Domain Regulates Transcription; NOTCH4 Intracellular Domain Regulates Transcription
Disease: Constitutive Signaling by NOTCH1 HD+PEST Domain Mutants; Constitutive Signaling by NOTCH1 PEST Domain Mutants
Developmental Biology: Cardiogenesis
Gene expression (Transcription): RUNX2 regulates osteoblast differentiation
Gene Ontology:
Molecular function: DNA-binding transcription factor activity; DNA-binding transcription factor activity, RNA polymerase II-specific; DNA-binding transcription repressor activity, RNA polymerase II-specific; histone deacetylase binding; protein binding; RNA polymerase II-specific DNA-binding transcription factor binding; sequence-specific DNA binding; sequence-specific double-stranded DNA binding; cis-regulatory region sequence-specific DNA binding; RNA polymerase II cis-regulatory region sequence-specific DNA binding; DNA binding; identical protein binding; protein dimerization activity
Biological process: negative regulation of DNA-templated transcription; negative regulation of transcription by RNA polymerase II; negative regulation of transcription initiation by RNA polymerase II; vascular associated smooth muscle cell development; anterior/posterior pattern specification; aortic valve morphogenesis; arterial endothelial cell differentiation; ascending aorta morphogenesis; atrial septum morphogenesis; cardiac conduction system development; cardiac epithelial to mesenchymal transition; cardiac left ventricle morphogenesis; cardiac right ventricle morphogenesis; cardiac septum morphogenesis; cardiac ventricle morphogenesis; circulatory system development; dorsal aorta morphogenesis; epithelial to mesenchymal transition involved in endocardial cushion formation; labyrinthine layer blood vessel development; mesenchymal cell development; muscular septum morphogenesis; negative regulation of biomineral tissue development; negative regulation of cardiac vascular smooth muscle cell differentiation; negative regulation of gene expression; negative regulation of Notch signaling pathway; and 18 more
Cellular component: transcription repressor complex; chromatin; cytoplasm; nucleoplasm; nucleus
Genetic constraint (gnomAD): Loss-of-function variants: 10 observed, 13.12 expected, observed/expected ratio (o/e) 0.76, 90% interval 0.47 to 1.29. The upper end of that interval is the gene's LOEUF score, 1.29, which puts it in group 5 of 6, group 1 being the genes least tolerant of losing a copy. Missense variants: 424 observed, 408.24 expected, observed/expected ratio (o/e) 1.04, 90% interval 0.96 to 1.12. Synonymous variants: 196 observed, 167.3 expected, observed/expected ratio (o/e) 1.17, 90% interval 1.04 to 1.32.
Gene-disease validity (ClinGen):
ClinGen rates the evidence that HEY2 causes each of these diseases.
congenital heart disease (autosomal dominant): Limited. A heart disease that is present at birth.
Homologues: Orthologues: chimpanzee HEY2 (100% identical), macaque HEY2 (99% identical), pig HEY2 (98% identical), rabbit HEY2 (96% identical), rat Hey2 (95% identical), mouse Hey2 (94% identical), guinea pig HEY2 (90% identical), tropical clawed frog hey2 (83% identical), dog HEY2 (78% identical), zebrafish hey2 (77% identical), Drosophila melanogaster E(spl)mgamma-HLH (15% identical), Drosophila melanogaster cwo (15% identical), and 7 more. Paralogues in human: HEY1 (52% identical), HEYL (41% identical), BHLHE41 (23% identical), HELT (22% identical), BHLHE40 (21% identical), HES1 (21% identical), HES4 (18% identical), HES6 (16% identical), HES7 (16% identical), HES3 (14% identical), HES2 (14% identical), HES5 (13% identical).
Diseases named in the same sentence as HEY2 in open-access papers:
HEY2 is named in the same sentence as 75 diseases in open-access papers, as found by Europe PMC text mining. Sharing a sentence is not in itself a finding about the gene and the disease. The quoted sentences say what the papers report.
breast cancer (11 papers, 2010 to 2025). A primary or metastatic malignant neoplasm involving the breast. "Included among these are Sirt1, Hey2, Ncoa4, and Foxa1, all of which have been implicated in the progression of luminal breast cancer and ER-α-dependent signaling, as well as ER-α (that is, Esr 1)." (PMID 20565980, 2010). "Interestingly, deletion of Jagged1 promoted mouse mammary tumor formation from luminal cells but suppressed them from basal cells, associated with downregulation of Notch target genes Hey1 and Hey2, respectively." (PMID 39890784, 2025). "In agreement with mouse experiments, high expression of JAG1 and HEY1 are associated with better overall survival among patients with luminal tumors, whereas high expression of JAG1 and HEY2 are both associated with worse overall survival in basal subtype of human breast cancer." (PMID 39890784, 2025). "Moreover, HEY2 overexpression is associated with poorer overall survival in basal breast cancer." (PMID 41463075, 2025). "Of note is the group of genes SP1, MYC, HEY2, E2F1, E2F2, and HES1, which are known to be associated with the KEGG breast cancer functional pathway." (PMID 40724805, 2025). "Leptin significantly elevated the expression levels of Notch1-4, Notch target genes, Hey2 and increased survival in breast cancer cells; in addition, leptin is an inducer of Notch signaling through regulating Notch1-4 expression and/or activation." (PMID 27185268, 2016). "CCL20-regulated PMN-MDSCs secrete large amounts of CXCL1 by binding to CXCR2 and activating the NOTCH1/HEY2 signaling pathway in BC cells, leading to an increase in breast cancer stem cells (BCSCs)." (PMID 38609997, 2024). "The overexpression of HIF-2α induced but miR-526b-3p repressed the expression of HIF-2α, Hey2, and Notch in PTX-treated breast cancer cells, while HIF-2α could reverse the effect of miR-526b-3p." (PMID 35004266, 2021). "Hypoxia-induced Notch activation promotes EMT in breast cancer cells, as shown by increased expression of Notch targets HEY2 and HES1, downregulation of E-cadherin and β-catenin, and increased cell migration and invasion of breast cancer cells cultured in low-oxygen conditions." (PMID 33003540, 2020). "Interestingly, the overexpression of HIF-2α induced but miR-526b-3p repressed the expression of HIF-2α, Hey2, and Notch in PTX-treated breast cancer cells, while HIF-2α could reverse the effect of miR-526b-3p." (PMID 35004266, 2021).
Brugada syndrome (11 papers, 2014 to 2025). A genetically heterogeneous condition characterized by complete or incomplete right bundle branch block accompanied by ST elevation in leads V1-V3. "Expression of the Hey2 gene, which is important for heart development and is linked to Brugada syndrome, a rare form of arrhythmia, was downregulated in the Notch3-/- hearts, which as expected also was the case for Notch3." (PMID 37699967, 2023). "For example, SRF、MYOCD are related to the development of cardiac vascular smooth muscle and molecular regulation of diseases, Mutations in HEY2 cause Brugada syndrome, a rare heart disease." (PMID 36303246, 2022). "In humans, HEY2 mutations are associated with Brugada syndrome, a ventricular arrhythmia, which can cause sudden death." (PMID 29636455, 2018). "Recently, it has been reported that Hey2 common variants are associated with Brugada Syndrome, a condition characterized by abnormal atrial and ventricular conduction resulting in arrhythmogenesis." (PMID 24667642, 2014). "Furthermore, the HEY2 gene is significantly expressed in vascular tissues and plays a role in vascular function; and was implicated in a previous migraine and recent Brugada syndrome (a potentially fatal heart rhythm disease) GWAS." (PMID 36292730, 2022). "Interestingly, the lead variant we have identified at this locus, rs10457469, is in high LD (r2 = 0.97) with rs9388451, which has been reported to be associated with Brugada syndrome through a HEY2-dependent alteration of ion channel expression across the cardiac ventricular wall." (PMID 32386560, 2020). "Recent studies have identified three common genetic variants associated with Brugada syndrome (BrS) near the genes SCN5A, SCN10A, and HEY2." (PMID 40338408, 2025). "Prior studies report protective variants against arrhythmia in the coding regions of the KCNQ1 and SCN5A genes and protective variants against Brugada syndrome in a coding region of the SCN10A gene and in a non-coding site downstream the HEY2 gene in the Japanese population." (PMID 33948580, 2021).
cardiac hypertrophy (8 papers, 2008 to 2024). "Hey2-deficient mice died within the first week after birth due to cardiovascular defects (ventricular septal defects, AV valve irregularities, and cardiac hypertrophy), but mice defective in Hey genes produced ectopic activation of atrial genes within the ventricular myocardium." (PMID 30464173, 2018). "It has been hypothesized that since a loss in function of CHF1/Hey2 results in cardiomyopathy, conversely, a gain in its function will protect against the manifestation of cardiac hypertrophy." (PMID 22758628, 2011). "For example, HEY2 expression levels influence cardiac hypertrophy and the progression to heart failure in response to pressure overload through modulation of apoptosis and GATA4 activity." (PMID 30816197, 2019). "Overexpression of CHF1/Hey2 in the myocardium was found to prevent phenylephrine-induced cardiac hypertrophy and expression of hypertrophy marker genes in vivo and in vitro." (PMID 22758628, 2011). "We have previously reported that the Hairy-related bHLH transcriptional repressor, CHF1 (also called Hey2, Hesr-2, Hrt2, HERP1 and gridlock), functions as a suppressor of cardiac hypertrophy induced by phenylephrine." (PMID 21119893, 2010). "Suppression of cardiac hypertrophy is mediated, at least in part, by the binding of CHF1/Hey2 to the transcription factor." (PMID 21119893, 2010). "Hey2-/- animals die around postnatal day 5 (P5) due to massive postnatal cardiac hypertrophy and isolated ventricular septal defects." (PMID 18302773, 2008). "Moreover, overexpression of HEY2 in the myocardium prevents PE-induced cardiac hypertrophy in vivo and in vitro." (PMID 26582913, 2016). "Interestingly, HEY2 knockout mice on a mixed genetic background develop cardiomyopathy with cardiac hypertrophy." (PMID 26582913, 2016). "In order to identify pathways relevant to cardiac hypertrophy in the cardiac myocyte transcriptome that are regulated by CHF1/Hey2, we examined the expression of genes in isolated wild type and transgenic myocytes treated with serum, a potent hypertrophic stimulus." (PMID 21119893, 2010). "We have found that CHF1/Hey2 regulates a number of gene sets that may play important roles in cardiac hypertrophy." (PMID 21119893, 2010). "These include genes involved in water transport (GO:0006833) such as aquaporins 2, 3, 5, 6, 7, 8, 9 and 11, suggesting that CHF1/Hey2 globally suppresses water transport and that water transport may be important for cardiac hypertrophy." (PMID 21119893, 2010). "These aggregate findings underscore the importance of CHF1/Hey2 in cardiac hypertrophy, and suggest that future therapies based on CHF1/Hey2 may have important therapeutic implications in preventing hypertrophy and heart failure." (PMID 21119893, 2010). "Foxm1 deletion did not alter mRNA expression of genes critical for cardiac hypertrophy and fibrosis such as α-SMA, collagen 1α1, CaMKIIδ, TNFα, BMP4, MMP9, CXCR4 and Hey2." (PMID 23144938, 2012).
glioma (7 papers, 2010 to 2024). A benign or malignant brain and spinal cord tumor that arises from glial cells (astrocytes, oligodendrocytes, ependymal cells). "Various studies have demonstrated increased expression of distinct components of Notch signaling pathway (such as Notch1, Notch2, Dll1, Dll4 and Jag1) and Notch target genes (Hey1, Hey2, Hes1) in glioma cell lines or primary human glioma samples including GBM." (PMID 36010607, 2022). "The potential role of the HEY2-based competitive endogenous RNA (ceRNA) regulatory network in glioma was validated and revealed the possible important role of glycolysis in glioma ERS." (PMID 36245971, 2022). "The TCGA data further confirmed the important regulatory value of the predicted HEY2/miR-369-3p/lncRNAs networks in glioma." (PMID 36245971, 2022). "BMP2 and HEY2 were identified as protective factors (HR < 1), and NUP107, DRAM1, F2R, PXDN, RNF19A, and SCG5 were identified as risk factors for glioma (HR > 1)." (PMID 36245971, 2022). "NOTCH2 overexpression can inhibit glioma formation in mouse glioma models and HEY2 overexpression can reduce the proliferation of murine and human glioma cells." (PMID 33076453, 2020). "The upregulation of Notch ligand JAG1 and targets Hey1, Hey2, Hes1 in brain tissues of glioma patients compared to that of healthy brain tissues also highlight the Notch signaling pathway as a potential therapeutic target in glioma patients." (PMID 33381038, 2020). "Integrated DNA and RNA analysis of low-grade and high-grade proneural gliomas identified increased expression and gene amplification of several genes including GLIS3, TGFB2, TNC, AURKA, and VEGFA in proneural GBMs, with corresponding loss of DLL3 and HEY2." (PMID 20838435, 2010). "SOX9 and HEY2, TFs associated with glioma stemness, were highly expressed in the Glioma-SPARCL1 population, suggesting that this population might consist of glioma stem cells." (PMID 38515213, 2024). "Consistent with our previous findings, the expressions of NUP107, DRAM1, RNF19A, PXDN, HEY2, F2R, and BMP2 were up-regulated in gliomas (glioblastoma multiforme + lower grade glioma)." (PMID 36245971, 2022). "A potential link between CRYAB, NOTCH1, and BMP pathways is also supported by diffuse low-grade glioma RNA profiles in the TCGA database, showing a significant correlation between CRYAB, BMP2, and HEY2 expression." (PMID 33925547, 2021).
glioblastoma (5 papers, 2013 to 2022). The most malignant astrocytic tumor (WHO grade IV). "We previously reported that in glioblastomas, NOTCH1 pathway activation led to the upregulation of HEY1 and HEY2 transcription factors." (PMID 33925547, 2021). "From these genes of particular interest are HEY2 with a role in notch signaling, LEFTY2 involved in TGFβ-signaling and IGFBP2 which is overexpressed in the stem cell compartment of glioblastomas promoting proliferation and survival of brain tumors." (PMID 24236059, 2013).
hepatocellular carcinoma (5 papers, 2013 to 2024). A malignant tumor that arises from hepatocytes. "In a study conducted by Dan-Chun Wu, HEY2 expression was significantly associated with poor overall and disease-free survival in patients with hepatocellular carcinoma (HCC), and its knockdown resulted in the opposite phenotype." (PMID 39684225, 2024). "It is reported that HEY2 binds to Smad3 and Smad4 promoters to inhibit the transcriptional activity of Smad3 and Smad4, and accelerates the malignant progression of hepatocellular carcinoma through TGF-β/Smad signaling pathway." (PMID 34127651, 2021). "Hey2 (Hairy/enhancer of split related with YRPW motif protein 2) is a transcription factor that is recently reported to play a critical role in cell proliferation and metastasis in hepatocellular carcinoma." (PMID 34588926, 2021).
lung carcinoma (5 papers, 2012 to 2025). "Notably, SIRT1-deficient lung cancer-derived ECs overexpressing N1IC displayed a markedly enhanced level of HEY1 and HEY2 activity." (PMID 23028940, 2012). "Expression levels of NOTCHs and their target genes (SNAI1, SNAI2, HES2, HEY2) are positively correlated with EMT scores in LUAD, indicating activation of the NOTCH pathway in mesenchymal lung cancer cells." (PMID 40189704, 2025). "In contrast, activation of SIRT1 signaling through the use of the small molecules SRT1720 or SRT2183 inhibited DLL4-mediated induction of HEY1 and HEY2 expression, indicating that SIRT1 negatively modulated DLL4/Notch1 signaling in lung cancer-derived ECs." (PMID 23028940, 2012). "Similarly, the silencing of SIRT1 significantly enhanced HEY1 and HEY2 expression in lung cancer-derived ECs in response to DLL4 stimulation, whereas no changes were observed in unstimulated lung cancer-derived ECs." (PMID 23028940, 2012).
osteosarcoma (5 papers, 2009 to 2024). A usually aggressive malignant bone-forming mesenchymal neoplasm, predominantly affecting adolescents and young adults. "Studies revealed that Notch pathway genes including Notch1, Notch2, Notch ligand DLL1, and Notch target genes including Hes-1, Hey-1, and Hey-2 were expressed in osteosarcoma cells." (PMID 34671398, 2021). "We found that Notch2, Jagged1, HEY1, and HEY2 were upregulated in the osteosarcoma biopsy specimens." (PMID 19455146, 2009). "In this study, we found that Notch2, Jagged1, HEY1, and HEY2 were overexpressed in human osteosarcoma specimens." (PMID 19455146, 2009).
cardiomyopathy (4 papers, 2010 to 2016). A disease of the heart muscle or myocardium proper. "Additional studies have underscored the importance of CHF1/Hey2 in the development of the myocardium, as loss of CHF1/Hey2 leads to a thin walled myocardium, cardiomyopathy and ectopic expression of atrial genes in the ventricular myocardium." (PMID 21119893, 2010).
hemangioma (4 papers, 2011 to 2024). A benign vascular lesion characterized by the formation of capillary-sized or cavernous vascular channels. "Protein expression evaluation by immunofluorescence confirms that HEY2 is expressed by HemECs (CD31+ cells), while HEY1, HEYL, and HES1 are more widely expressed and mostly expressed by perivascular cells of hemangiomas." (PMID 21834989, 2011). "Although the role of HEY2 in human cancer has not been identified, overexpression of HEY2 has been reported in prostate cancer, pancreatic ductal adenocarcinomas and hemangioma." (PMID 27191260, 2016).
melanoma (4 papers, 2023 to 2024). A malignant, usually aggressive tumor composed of atypical, neoplastic melanocytes. "The heatmap was used to demonstrate the expression levels of the genes TBX21, ZNF799, HEY2, ZNF580, IRF4, CREB3, and ZNF93 during the pseudotime trajectories of four distinct subtypes of melanoma cells." (PMID 37435067, 2023). "LASSO regression analysis was used to filter TFs further in order to identify a biomarker that could predict the prognosis of patients with melanoma, based on which seven TFs (TBX21, MYB, GFI1, NFE2L3, TFAP2C, HEY2, NR2F2) were selected." (PMID 37435067, 2023). "Importantly, Notch4 may induce suppression of Snail2 and Twist1 through downstream Hey1 and Hey2 targets and is non-canonically mediated in WM9 and WM164 melanoma cell lines." (PMID 37108670, 2023).
Arrhythmia (3 papers, 2016 to 2021). Any cardiac rhythm other than the normal sinus rhythm. "An association of the HEY2 risk allele was found with cardiac arrest/VF in the larger UK Biobank population indicating a possible pathological role in cardiac arrhythmia." (PMID 30042696, 2018). "Genetic variants at the SCN5A, HEY2, and SCN10A loci have been associated with arrhythmia occurrence in independent studies." (PMID 27200363, 2016).